PRSS3 (serine protease 3)
Description:
Digestive protease that cleaves proteins preferentially after an Arg residue and has proteolytic activity toward Kunitz-type trypsin inhibitors.
Synonyms: PRSS4; TRY3; TRY4; MTG; T9
Tractability: Small molecule: a structure with a bound ligand is known; a high-quality ligand is known; it belongs to a druggable protein family. Antibody: UniProt places it where antibodies can reach, with high confidence; its Gene Ontology location is reachable by antibodies, with high confidence; UniProt predicts a signal peptide or a membrane-spanning region. PROTAC: ubiquitination databases record sites on it; a small molecule that binds it is known.
Target class: Serine protease; Enzyme; Serine protease PA clan; Serine protease S1A subfamily; Protease
Gene: Protein-coding gene on chromosome 9 (33,750,679 to 33,799,231, forward strand). Ensembl gene ENSG00000010438.
Subcellular location: Secreted
Subcellular location (Human Protein Atlas): Vesicles; Endoplasmic reticulum; Predicted to be secreted
Pathways (Reactome):
Immune System: Alpha-defensins; Antimicrobial peptides; Neutrophil degranulation
Developmental Biology: Differentiation of Keratinocytes in Interfollicular Epidermis in Mammalian Skin
Metabolism: Uptake of dietary cobalamins into enterocytes
Gene Ontology:
Molecular function: calcium ion binding; protein binding; serine-type endopeptidase activity; serine-type peptidase activity
Biological process: endothelial cell migration; proteolysis; zymogen activation; antimicrobial humoral response; digestion
Cellular component: extracellular region; tertiary granule lumen
Genetic constraint (gnomAD): Loss-of-function variants: 19 observed, 22.88 expected, observed/expected ratio (o/e) 0.83, 90% interval 0.58 to 1.22. The upper end of that interval is the gene's LOEUF score, 1.22, which puts it in group 5 of 6, group 1 being the genes least tolerant of losing a copy. Missense variants: 237 observed, 288.28 expected, observed/expected ratio (o/e) 0.82, 90% interval 0.74 to 0.92. Synonymous variants: 91 observed, 105.33 expected, observed/expected ratio (o/e) 0.86, 90% interval 0.73 to 1.03.
Homologues: Orthologues: chimpanzee PRSS3 (94% identical), pig PRSS2 (79% identical), mouse Prss3l (77% identical), mouse Try5 (77% identical), mouse Prss1 (77% identical), mouse Prss1l (77% identical), mouse Try10 (77% identical), rat Prss3 (77% identical), mouse Prss3 (77% identical), mouse Try4 (77% identical), rat Prss2 (76% identical), rat Prss2l1 (76% identical), and 6 more. Paralogues in human: PRSS2 (87% identical), PRSS1 (85% identical), PLAU (40% identical).
Diseases named in the same sentence as PRSS3 in open-access papers:
PRSS3 is named in the same sentence as 60 diseases in open-access papers, as found by Europe PMC text mining. Sharing a sentence is not in itself a finding about the gene and the disease. The quoted sentences say what the papers report.
pancreatic cancer (13 papers, 2013 to 2025). "In pancreatic cancer, secreted PRSS3 activity is linked to increased invasiveness of cancer cells by facilitating the degradation of the extracellular matrix, enabling cells to invade surrounding tissues." (PMID 39858031, 2025). "In this study, we used TCGA and GEO datasets to construct 5-mRNA signature (ANKRD22, ARNTL2, DSG3, KRT7, PRSS3) that is associated with the prognosis of pancreatic cancer patients." (PMID 36906533, 2023). "The elevated expression of PRSS3 is associated with a poor prognosis for multiple cancers, including lung adenocarcinoma, gastric cancer, ductal carcinoma of the breast, and pancreatic cancer." (PMID 35860586, 2022). "Interleukin 22 receptor subunit alpha 1 (IL22RA1) and protease serine 3 (PRSS3) were associated with chronic pancreatitis in mouse models and with progression, metastasis, and prognosis of human pancreatic cancer." (PMID 31565069, 2019). "In pancreatic cancer, the research data showed that the expression of PRSS3 and lymph node metastasis, as well as distant metastasis, were closely related." (PMID 28423522, 2017). "Over-expression of PRSS3 has been shown to promote pancreatic cancer cell proliferation as well as invasion in vitro, and tumor progression and metastasis in vivo." (PMID 24146905, 2013). "For example, PRSS3 was identified to be downregulated in lung cancer but upregulated in pancreatic cancer, suggesting that it may have different roles depending on the cellular or disease ways." (PMID 41247789, 2025). "The high expression of PRSS3 was also identified in breast cancer tissues and pancreatic cancer." (PMID 40565234, 2025). "A machine learning based-study reported that the 5-gene signature including ANKRD22, ARNTL2, DSG3, KRT7, PRSS3 performed well on both our chosen training dataset and validation dataset and provided a new way to predict the prognosis of pancreatic cancer patients." (PMID 38184732, 2024). "High expression of EPYC, ANKRD22, ARNTL2, DSG3, KRT7, PRSS3 and MET predict poor prognosis of pancreatic cancer patients." (PMID 38184732, 2024). "Interestingly, PRSS3 was only observed to be overexpressed in metastatic pancreatic cancer cells but not in nonmetastatic pancreatic cancer cells." (PMID 36618965, 2022).
gastric cancer (9 papers, 2010 to 2025). A primary or metastatic malignant neoplasm involving the stomach. "The expression of PRSS3 is reduced in bladder, esophageal, and gastric cancers, and loss of PRSS3 expression is due to epigenetic silencing through promoter hypermethylation." (PMID 21203532, 2010). "Several articles have reported an increased expression of PRSS3 (mesotrypsin) in various human digestive pathologies, including colon adenocarcinoma, gastric cancer, irritable bowel syndrome, or pancreatitis." (PMID 37931399, 2023). "Among the identified DEGs, we found that 7 genes (IGFBP7, LOX, NRP1, PRSS3, DPP3, EFNA3, and CD73) were also differentially expressed in tumor tissues and associated with a poor or better prognosis in patients with gastric cancer." (PMID 34659527, 2021). "Similar findings were observed in several other cancer types on that PRSS3 overexpression could serve as a survival predictor of ovarian cancer, gastric cancer, and colon cancer." (PMID 36618965, 2022). "According to Wang's findings, increased PRSS3 expression may enhance stomach cancer metastasis and serve as an independent molecular indication of poor patient prognosis." (PMID 36056349, 2022). "While a study of esophageal squamous cell carcinoma found that promoter methylation can silence the expression of PRSS3, some other studies reported that methylation of the PRSS3 promoter in bladder cancer, lung cancer, esophageal cancer, and gastric cancer also silence its expression." (PMID 28423522, 2017).
lung carcinoma (9 papers, 2017 to 2025). "To assess whether expression of PRSS3 may play a functional role in promoting malignant progression of LAC, we first examined PRSS3 expression in a small panel of established lung cancer cell lines." (PMID 30755669, 2019). "In addition, overexpression of PRSS3 in lung-cancer tissue results in increased migration across endothelial cells, thereby highlighting the potential role of trypsin in tumor metastasis." (PMID 28423522, 2017). "These bioinformatic analyses provided further evidence on the clinical relevance between SS‐elevated gene expression of PRSS3, PAR2, and FOSL1 and lung cancer." (PMID 37395651, 2023). "Higher protein levels of PRSS3, PAR2, FRA1, p‐FRA1, cJUN, and p‐cJUN were also detected in cells of another lung cancer cell line H1975 after circulation." (PMID 37395651, 2023). "Together, these results unveil the clinical significance of PRSS3, PAR2, and FOSL1 and suggest that they may serve as new biomarkers for the diagnosis and treatment of lung cancer metastasis." (PMID 37395651, 2023). "Moreover, we demonstrated that SS induced the high expression of PRSS3, but not PRSS1 or PRSS2, in circulating lung cancer cells to facilitate metastasis, suggesting a crucial role of PRSS3 in metastasis‐initiating CTCs." (PMID 37395651, 2023).
breast carcinoma (8 papers, 2013 to 2025). "Consistent with our data, knockdown of PRSS3 attenuates, while stimulation with recombinant purified mesotrypsin enhances, the proliferation of breast cancer." (PMID 36618965, 2022). "created an HMT-3522 breast cancer–growth model under 3-dimentional organ culture conditions and found that the expression of PRSS3 in breast cancer cell line T4-2 was enhanced." (PMID 28423522, 2017). "Supportive evidence was found in breast cancer where PRSS3/mesotrypsin is upregulated in malignant T4-2 cells as compared to their nonmalignant progenitors." (PMID 24146905, 2013). "Importantly, PRSS3/MTG linked to F2RL1 (also known as PAR2), was reported to modulate inflammation and tumorigenesis in several cancer types, such as colon cancer and breast cancer." (PMID 35480112, 2022). "In human breast cancer, cathepsin D (CTSD), IL4 receptor (IL4R), mucin-1 (MUC1, CD227), and serine protease 3 (PRSS3) may serve as valuable biomarkers for the diagnosis and treatment of breast cancer." (PMID 35787690, 2022). "PRSS3 was found to promote the growth of breast cancer cells." (PMID 31195961, 2019).
prostate carcinoma (6 papers, 2015 to 2024). A carcinoma that arises from epithelial cells of the prostate gland. "While one previous study found that mesotrypsin, a protease encoded by the PRSS3 gene, was essential for prostate cancer metastasis in vitro and mouse models, the role of this protein and other isoforms have not been widely studied in humans." (PMID 38878676, 2024). "The protease PRSS3 is the first to link the enzyme to prostate cancer, leading to the development of a compound to stop PRSS3 from promoting metastasis." (PMID 35480112, 2022). "In prostate cancer experimental studies, knockdown of PRSS3/mesotrypsin expression inhibited anchorage independent growth and invasion of cancer cells, and suppressed metastasis in orthotopic mouse models." (PMID 30755669, 2019). "By reducing the expression of PRSS3, lung metastasis of prostate cancer would be significantly inhibited." (PMID 28423522, 2017). "Active trypsin 4 has never been detected in cancer, but few reports suggest the higher expression of PRSS3 (i.e. mRNA by microarray) associated with a worse prognosis in NSCL, pancreatic, and prostate cancer." (PMID 26318044, 2015).
bladder cancer (5 papers, 2010 to 2020). "In particular, silencing of PRSS3 by promoter methylation has been significantly associated with invasive tumor stage in bladder cancer." (PMID 21203532, 2010). "Specifically, RASSF1A and PRSS3 promoter methylation is associated with advanced tumor stage, which suggests that these genes might be associated with bladder cancer progression." (PMID 21203532, 2010). "Promoter methylation of p16 (INK4A), RASSF1A, and PRSS3 occurs in approximately 30% of cases of bladder cancer; promoter methylation of both RASSF1A and PRSS3 is associated with advanced tumor stage." (PMID 28587272, 2017). "In bladder cancer, there is a relationship between epigenetic silencing of the tumor-suppressor genes p16 (INK4A), RASSF1A, PRSS3, and the four SFRP genes and exposure to both tobacco and arsenic." (PMID 28587272, 2017).
epithelial ovarian cancer (5 papers, 2017 to 2025). "Previous studies have established the role of PRSS3 in the progression of pancreatic and ovarian cancer." (PMID 28362259, 2017). "Interestingly, the expression of PRSS3 showed a significant increase in epithelial ovarian cancer tissue compared to normal ovarian samples at mRNA and protein levels." (PMID 35038288, 2022).
colon carcinoma (4 papers, 2008 to 2025). "All five colon carcinoma cell lines expressed PRSS3 at the same level, slightly lower than the median level of primary tumors." (PMID 40909962, 2025). "Correlations between levels of PRSS3 and PRSS22 mRNAs and CEA, CXCL16, CXCL17, GPR35 V2/3, LGR5, LGR6 and KLK6 mRNA levels in lymph nodes of colon cancer patients." (PMID 40909962, 2025). "Pairwise comparisons of levels in the primary tumor and the highest lymph node of PRSS3 and PRSS22 mRNAs in colon cancer patients." (PMID 40909962, 2025). "The predictive efficacy of proteases PRSS3 and PRSS22 mRNA levels for predicting relapse in surgically treated colon cancer (CC) patients was assessed." (PMID 40909962, 2025). "Our search in the RefExA and SOURCE databases revealed that PRSS3 was not expressed by tumor cells, with the exception of colon carcinoma." (PMID 18447899, 2008). "Specifically, their expression in the carcinoma cell lines (1A9 and SKOV3 ovarian, MDA-MB-431 breast and HT29 colon) was not or was barely detectable (with the exception of PRSS3 by the HT29 colon carcinoma)." (PMID 18447899, 2008).
lung adenocarcinoma (4 papers, 2019 to 2023). A carcinoma that arises from the lung and is characterized by the presence of malignant glandular epithelial cells. "Limiting the analysis to the subset of patients with lung adenocarcinoma (LAC) resulted in greater hazard ratios relating PRSS3 expression with poor OS (HR 2.22, P = 9e-12) and poor PFS (HR 2.26, P = 2.7e-7)." (PMID 30755669, 2019). "Here we implicate a signaling pathway consisting of PRSS3/mesotrypsin and kallikrein-related peptidase 5 (KLK5) in lung adenocarcinoma malignancy." (PMID 30755669, 2019). "We further show that genetic targeting of KLK5, a known target of PRSS3/mesotrypsin, phenocopies the effect of PRSS3/mesotrypsin knockdown, and also that elevated expression of KLK5 is similarly prognostic for outcome in lung adenocarcinoma." (PMID 30755669, 2019).
esophageal adenocarcinoma (3 papers, 2013 to 2022). A malignant tumor with glandular differentiation arising predominantly from Barrett mucosa in the lower third of the esophagus. "Another example is that targeting the PRSS3 in conjunction with current 5-Fu therapy provides further inhibition effects in esophageal adenocarcinoma." (PMID 36618965, 2022). "We found that esophageal adenocarcinoma cells (EACs) and Barrett’s Metaplasia (BART) expressed high levels of type 3 extra-pancreatic trypsinogen (PRSS3), a novel type of TAT." (PMID 24146905, 2013).
thyroiditis (2 papers, 2022 to 2025). Inflammation of the thyroid gland. "The PRSS3 gene is located on the locus of T-cell receptor beta variable orphan on chromosome 9 ‘[cytogenetic location: 9p13.3; genomic coordinates (GRCh37/hg19) 33750677-33799229] and is associated with thyroiditis and Rickettsialpox." (PMID 35860586, 2022). "Diseases associated with PRSS3 include thyroiditis and Hashimoto thyroiditis." (PMID 35860586, 2022).
benign ovarian tumors (1 paper, 2017). "PRSS3 was expressed in both ovarian epithelial cancer and benign ovarian tumors, but its expression was significantly higher in ovarian epithelial cancer." (PMID 28423522, 2017).
cholangiocarcinoma (1 paper, 2024). A carcinoma that arises from the intrahepatic biliary tree (intrahepatic cholangiocarcinoma) or from the junction, or adjacent to the junction, of the right and left hepatic ducts (hilar cholangiocarcinoma). "We aimed to investigate the potential antitumor effect of upamostat and opaganib, individually and in combination, on CCA patient-derived xenografts (PDX) in nude mice using PAX165, a cholangiocarcinoma PDX that expresses substantial levels of SPHK2, PRSS1, PRSS2, and PRSS3." (PMID 38473407, 2024).
glioblastoma (1 paper, 2022). The most malignant astrocytic tumor (WHO grade IV). "For examples, human PRSS1 (cationic trypsinogen) is one of the EV-A71 IRES-associated proteins in human glioblastoma T98G cells and the cleavage of hemagglutinin (HA) by activated human trypsinogen (PRSS3) enhanced influenza A virus infection." (PMID 35896602, 2022).
head and neck cancer (1 paper, 2017). A primary or metastatic malignant neoplasm affecting the head and neck. "Based on the TCGA exome set, we observe a significantly decreased survival for head and neck cancer (HNSC) samples mutated in the promoter region of PRSS3 (p=1.8 × 10−3, Log-rank test) as well as in the PRSS3 coding gene (p=1.2 × 10−2, Log-rank test)." (PMID 28362259, 2017).
IgA nephropathy (1 paper, 2026). "Transcriptomic-wide MR identified candidate genes across GN subtypes: RECQL, BRSK2, and MGP in acute GN; AFM, CFHR5, and EPHB2 in chronic GN; IL6R, MBL2, and PRSS3 in IgA nephropathy; and TIMP4, HCK, and PEAR1 in membranous nephropathy." (PMID 41990104, 2026).
invasive ductal carcinoma (1 paper, 2017). "PRSS3 protein levels in invasive ductal carcinoma of the breast tissues were correlated with the clinical characteristics of patients with invasive ductal carcinoma of the breast and their 5.0-year survival rate." (PMID 28423522, 2017). "Both PRSS3 mRNA and protein levels were significantly higher in invasive ductal carcinoma of the breast tissues than in normal or benign tissues (all P < 0.05)." (PMID 28423522, 2017). "The objective of this study was to determine PRSS3 mRNA and protein expression levels in invasive ductal carcinoma of the breast and normal surrounding tissue samples." (PMID 28423522, 2017). "We sought to determine both the mRNA and protein expression of PRSS3 in invasive ductal carcinoma of the breast (IDC) tissue samples and correlate this with the patient's clinical characteristics and 5.0-year survival rate." (PMID 28423522, 2017). "PRSS3 acts as an oncogene in invasive ductal carcinoma of the breast development and progression." (PMID 28423522, 2017). "In our study, real-time quantitative polymerase chain reaction (qPCR) and tissue microarray immunohistochemistry analysis (TMA-IHC) were used to determine the mRNA and PRSS3 expression, respectively, in invasive ductal carcinoma of the breast from tissue samples." (PMID 28423522, 2017).
neuroblastoma (1 paper, 2022). Neuroblastoma (NB) is the most common solid, extracranial childhood tumor. "The direct protein–protein interaction between homo sapiens serine protease 3 (PRSS3), the PRSS3 transcript variant 3 or mesotrypsin, derived from the human neuroblastoma SH-SY5Y cell and the recombinant EV-A71 3A protein (FLAG-3A-mCherry) was confirmed." (PMID 35896602, 2022). "Because of the low transfection efficiency of human neuroblastoma SH-SY5Y-cells, HEK293T cell was selected for use as a model for studying the role of PRSS3 in EV-A71 replication." (PMID 35896602, 2022).
Obesity (1 paper, 2021). Accumulation of substantial excess body fat. "The “weight loss” group also showed decreased levels of APOE, C5, CRP, LBP, NEGR1, and PRSS3, which have all been positively associated with obesity, inflammation, and metabolic disorders (22, –, 26)." (PMID 34519531, 2021).
psoriasis (1 paper, 2024). An autoimmune condition characterized by red, well-delineated plaques with silvery scales that are usually on the extensor surfaces and scalp. "Finally, through Cellchat and correlation analysis, we identified PRSS3-F2R as potentially promoting the expression of hub genes in the psoriasis group, thereby enhancing keratinocyte-fibroblast interaction, ultimately driving psoriasis occurrence and progression." (PMID 38699235, 2024).